OR5T3 (olfactory receptor family 5 subfamily T member 3)
Description:
Odorant receptor.
Synonyms: OR5T3Q; OR11-178
Gene: Protein-coding gene on chromosome 11 (56,252,254 to 56,253,222, forward strand). Ensembl gene ENSG00000172489.
Subcellular location: Cell membrane
Genetic constraint (gnomAD): Loss-of-function variants: 13 observed, 14.1 expected, observed/expected ratio (o/e) 0.92, 90% interval 0.6 to 1.46. The upper end of that interval is the gene's LOEUF score, 1.46, which puts it in group 6 of 6, group 1 being the genes least tolerant of losing a copy. Missense variants: 395 observed, 369.21 expected, observed/expected ratio (o/e) 1.07, 90% interval 0.98 to 1.16. Synonymous variants: 138 observed, 134.49 expected, observed/expected ratio (o/e) 1.03, 90% interval 0.89 to 1.18.
Homologues: Orthologues: mouse Or5t5 (78% identical), rat Or5t5 (78% identical), mouse Or5t9 (76% identical), rat Or5t5b (76% identical), rat Or5t9b (74% identical), mouse Or5t17 (74% identical), Caenorhabditis elegans ser-5 (15% identical), zebrafish adra1ab (15% identical). Paralogues in human: OR5T1 (81% identical), OR5T2 (73% identical), OR13F1 (42% identical), OR56A1 (28% identical), OR56A4 (28% identical), OR56A3 (28% identical), OR56A5 (27% identical), ADRA2A (19% identical), ADRA2B (18% identical), ADRA2C (18% identical), ADRA1B (17% identical), ADRA1D (17% identical), and 6 more.